CT55 (cancer/testis antigen 55)
Description:
Plays a role in spermatogenesis, possibly acting in the regulation of the autophagy pathway.
Synonyms: CXorf48; FLJ20527; BJHCC20A; SPGFX7
Tractability: No criterion of Open Targets' tractability assessment is met for any kind of drug.
Gene: Protein-coding gene on chromosome X (135,156,540 to 135,171,398, reverse strand). Ensembl gene ENSG00000169551.
Subcellular location: Cytoplasm; Cytoplasmic vesicle, secretory vesicle, acrosome; Cell projection, cilium, flagellum
Subcellular location (Human Protein Atlas): Vesicles
Gene Ontology:
Molecular function: protein binding
Biological process: spermatogenesis
Cellular component: acrosomal vesicle; cytoplasm; sperm flagellum; motile cilium
Homologues: Orthologues: chimpanzee CT55 (98% identical), macaque CXHXorf48 (91% identical), chimpanzee CT55 (58% identical), rat LOC120099287 (41% identical), Drosophila melanogaster CG6701 (16% identical), Drosophila melanogaster armi (10% identical), zebrafish setx (9% identical), Drosophila melanogaster Mov10 (7% identical), Caenorhabditis elegans sosi-1 (6% identical), zebrafish dna2 (6% identical), Drosophila melanogaster Dna2 (6% identical), Caenorhabditis elegans Y106G6D.5 (6% identical), and 2 more. Paralogues in human: MOV10L1 (50% identical), HELZ2 (16% identical), SETX (11% identical), HELZ (11% identical), MOV10 (11% identical), ZNFX1 (11% identical), AQR (9% identical), DNA2 (8% identical), UPF1 (5% identical), IGHMBP2 (4% identical).
Diseases named in the same sentence as CT55 in open-access papers:
CT55 is named in the same sentence as 17 diseases in open-access papers, as found by Europe PMC text mining. Sharing a sentence is not in itself a finding about the gene and the disease. The quoted sentences say what the papers report.
breast carcinoma (2 papers, 2016 to 2019). "Another study showed that the downregulation of endogenous CT55 expression suppresses breast cancer cell growth and leads to the induction of apoptosis." (PMID 30944312, 2019).
colorectal cancer (2 papers, 2016 to 2019). A primary or metastatic malignant neoplasm that affects the colon or rectum. "Altogether, our results indicate that Ct55 deficiency alleviates the inflammatory response and inhibits cell proliferation during colitis-associated colorectal cancer." (PMID 30944312, 2019). "RNA-seq analysis and western blotting showed that Ct55 deficiency played a protective role in colitis-associated colorectal cancer by regulating TNF-α-induced NF-κB signaling." (PMID 30944312, 2019). "To verify the hypothesis that Ct55 may function in colitis-associated colorectal cancer by targeting TNF-α-induced NF-κB signaling, we detected the expression levels of p-p65 and other indicated proteins by western blot." (PMID 30944312, 2019). "In our study, we found that CT55 expression was elevated in human colorectal cancer, whereas it was low in normal mouse tissues, except for the testis." (PMID 30944312, 2019). "Since Ct55 deficiency alleviates AOM/DSS-induced colitis-associated tumorigenesis, we then assessed the role of CT55 in the growth of colorectal cancer cells, and HCT116 CT55 KO cell lines were prepared using CRISPR/Cas9-mediated genome editing." (PMID 30944312, 2019). "To explore whether CT55 is involved in colorectal cancer, we first detected CT55 expression in 12 paired colon and adjacent nontumor human colon tissues." (PMID 30944312, 2019). "Because CT55 expression was higher in colorectal cancer than in normal colorectal tissue, it is important to investigate whether CT55 serves as a regulator in colorectal cancer." (PMID 30944312, 2019).
colitis (1 paper, 2019). Inflammation of the colon. "We aimed to gain further insight into the full spectrum of Ct55 functions in AOM/DSS-induced colitis-associated tumorigenesis at the molecular level." (PMID 30944312, 2019). "Surprisingly, we found that Ct55-deficient mice were resistant to colitis-associated tumorigenesis in the animal AOM/DSS model by targeting TNF-α-induced NF-κB signaling." (PMID 30944312, 2019). "In our study, we observed that CT55 is closely associated with CAC and that Ct55 deficiency alleviated inflammatory responses and decreased cell proliferation and colitis-associated tumorigenesis in a mouse AOM/DSS model." (PMID 30944312, 2019). "The widely used AOM/DSS model of colitis-associated colorectal tumorigenesis was applied, and WT and Ct55 knockout mice were used for the modeling." (PMID 30944312, 2019). "We discovered that Ct55 deficiency alleviated inflammatory responses, decreased cell proliferation and colitis-associated tumorigenesis in an azoxymethane/dextran sulfate sodium (AOM/DSS) mouse model." (PMID 30944312, 2019). "Consistent with previous studies, Ct55-deficient mice showed decreases in the incidence and size of colitis-associated tumors as a consequence of decreased NF-κB activity." (PMID 30944312, 2019). "Specifically, we found that Ct55-deficient mice were resistant to CAC in a colitis-associated colon cancer model." (PMID 30944312, 2019). "Taken together, these observations suggest that Ct55 deficiency alleviates AOM/DSS-induced colitis-associated tumorigenesis." (PMID 30944312, 2019). "Ct55 deficiency is known to alleviate AOM/DSS-induced colitis-associated tumorigenesis." (PMID 30944312, 2019). "Accordingly, combined with the results of RNA-seq in mouse colitis, our study showed that CT55 could regulate the production of TNF-α by affecting NF-κB activation in HCT116 cells, which might explain how CT55 functions in CAC." (PMID 30944312, 2019). "Given the finding that Ct55 significantly decreased the inflammatory response in the AOM/DSS model and its reported role in immunotherapy, we performed RNA-seq analysis of the mouse colon samples obtained from Ct55 knockout and WT mice that underwent DSS colitis experiments." (PMID 30944312, 2019).
Rectal prolapse (1 paper, 2019). Protrusion of the rectal mucous membrane through the anus. "Moreover, the symptom of rectal prolapse was attenuated in Ct55 knockout mice compared with the WT control, and we observed that there was a lower incidence of rectal prolapse in Ct55-deficient mice, which is 14.3% (6 out of 15) in contrast to 40% (6 out of 15) in WT mice at 60 days in our model." (PMID 30944312, 2019).
cancer (4 papers, 2016 to 2022). A tumor composed of atypical neoplastic, often pleomorphic cells that invade other tissues. "CT55 is also a member of the cancer testicular antigen family, and studies have found that CT55 deficiency inhibits the NF-KB signaling pathway, thereby attenuating colitis-associated cancers." (PMID 35651938, 2022). "Previous studies have suggested that CT55 is a potential CT antigen and that CT55 is expressed in several cancers and normal testis." (PMID 30944312, 2019). "Several reports have indicated that CT55 is highly expressed in several cancers, including colorectal cancer." (PMID 30944312, 2019).
tumor (3 papers, 2015 to 2020). "In our experiments, not only the tumor incidence but also the tumor size were decreased in Ct55-deficient mice." (PMID 30944312, 2019). "Also, the weight of CT55-deficient xenograft tumors at sacrifice was smaller in contrast to control, suggesting that CT55 deficiency effectively suppressed tumor growth in nude mice." (PMID 30944312, 2019). "Consistently, the tumor incidence and size were also decreased in the Ct55-deficient mice." (PMID 30944312, 2019). "Consistently, we also found that the percentages of β-catenin-, PCNA- and cyclin D1-positive cells in the tumor tissues of Ct55 knockout mice were lower than those in the WT mice after AOM/DSS treatment." (PMID 30944312, 2019). "The mRNA expression levels of COX2, TNF-α, Il-6, and Ccl2 were significantly decreased in the tumor tissues of the Ct55 knockout mice compared with those of the WT mice." (PMID 30944312, 2019). "Decreased expression levels of the proliferation-related genes PCNA and cyclin D1 were observed in the tumor tissues of Ct55 knockout mice by qRT-PCR." (PMID 30944312, 2019). "Furthermore, the number of Ki-67-positive cells was significantly decreased in the tumor tissues of Ct55 knockout mice via Ki-67 staining." (PMID 30944312, 2019). "Further experiments are needed to determine whether Ct55 regulates tumor size by affecting NF-κB activation in inflammatory cells." (PMID 30944312, 2019). "Therefore, hematoxylin and eosin staining was performed, and the results showed less inflammatory in Ct55 knockout mouse tumor tissues than in WT mouse tissues." (PMID 30944312, 2019). "Moreover, it is well known that many cytokines, such as TNF-α, COX2, and IL6, can regulate carcinogenesis by affecting cell proliferation and apoptosis; thus, the production of cytokines was examined by quantitative real-time PCR (qRT-PCR) in the tumor tissues of Ct55 knockout and WT mice." (PMID 30944312, 2019). "Interestingly, the mRNA level of CT55 was upregulated by at least two-fold in 6 out of 12 tumor tissues compared to the paired nontumor tissues." (PMID 30944312, 2019).
CT55 also shares sentences with these, for which no sentence is quoted: cervical cancer (2 papers); chronic myelogenous leukaemia (2); lung carcinoma (2); melanoma (2); multiple myeloma (2); colon cancer (1); esophageal squamous cell carcinoma (1); gastric cancer (1); head and neck squamous cell carcinoma (1); hematological malignancies (1); myeloid leukemia (1).